Y_RNA (Y RNA )
Gene: Miscellaneous RNA gene on chromosome 11 (34,189,174 to 34,189,275, forward strand). Ensembl gene ENSG00000201867.
Homologues: Orthologues: chimpanzee Y_RNA (100% identical), macaque Y_RNA (96% identical). Paralogues in human: Y_RNA (89% identical), Y_RNA (88% identical), Y_RNA (87% identical), Y_RNA (86% identical), RNY3 (85% identical), RNY3P1 (85% identical), Y_RNA (85% identical), Y_RNA (84% identical), Y_RNA (83% identical), RNY3P11 (82% identical), RNY3P16 (82% identical), RNY3P5 (82% identical), and 97 more.